TRAJ54 (T cell receptor alpha joining 54)
Gene: T-cell receptor joining (J) gene on chromosome 14 (22,482,287 to 22,482,346, forward strand). Ensembl gene ENSG00000211836.
Diseases named in the same sentence as TRAJ54 in open-access papers:
TRAJ54 is named in the same sentence as 1 disease in open-access papers, as found by Europe PMC text mining. Sharing a sentence is not in itself a finding about the gene and the disease. The quoted sentences say what the papers report.
COVID-19 (1 paper, 2021). A disease caused by infection with severe acute respiratory syndrome coronavirus 2. "In the CD4+ T cells of COVID-19 patients at the two-week convalescent stage, 37 unique pairs of VJ rearrangement of TRA were found, such as TRAV8-4/TRAJ54 and TRAV17/TRAJ54, and 23 specific pairs of TRB VDJ patterns were also found in CD4+ T cells." (PMID 35011632, 2021).